GPR4 (G protein-coupled receptor 4)
Description:
Proton-sensing G protein-coupled receptor activated by extracellular pH, which is required to monitor pH changes and generate adaptive reactions. Activated by an optimal pH of 6.8-7.2. Ligand binding causes a conformation change that triggers signaling via guanine nucleotide-binding proteins (G proteins) and modulates the activity of downstream effectors, such as adenylate cyclase. GPR4 is mainly coupled to G(s) G proteins and mediates activation of adenylate cyclase activity. May also couple with G(i), G(q) and G(12)/G(13) G proteins. Acts as a key regulator of respiratory sensitivity to CO2/H(+) in brain retrotrapezoid nucleus neurons: acts by mediating detection of protons generated by the formation of carbonic acid in the blood, an important mechanism to impulse to breathe (By similarity). Also acts as a regulator of acid secretion in the kidney collecting duct by maintaining acid-base homeostasis in the kidney (By similarity). Acidosis-induced GPR4 activation increases paracellular gap formation and permeability of vascular endothelial cells, possibly through the G(12)/G(13)/Rho GTPase signaling pathway.
Synonyms: hGPR4; GPR6C.l
Tractability: Small molecule: a high-quality ligand is known; it belongs to a druggable protein family. Antibody: UniProt places it where antibodies can reach, with high confidence; its Gene Ontology location is reachable by antibodies, with high confidence; UniProt predicts a signal peptide or a membrane-spanning region. PROTAC: a small molecule that binds it is known.
Target class: Family A G protein-coupled receptor; Membrane receptor
Gene: Protein-coding gene on chromosome 19 (45,589,764 to 45,602,556, reverse strand). Ensembl gene ENSG00000177464.
Subcellular location: Cell membrane
Pathways (Reactome):
Signal Transduction: Class A/1 (Rhodopsin-like receptors); G alpha (q) signalling events
Gene Ontology:
Molecular function: G protein-coupled receptor activity; protein binding
Biological process: adenylate cyclase-activating G protein-coupled receptor signaling pathway; cellular response to acidic pH; phospholipase C-activating G protein-coupled receptor signaling pathway; positive regulation of Rho protein signal transduction; regulation of cell adhesion; response to acidic pH; G protein-coupled receptor signaling pathway; positive regulation of inflammatory response; regulation of vascular permeability
Cellular component: plasma membrane; membrane
Genetic constraint (gnomAD): Loss-of-function variants: 13 observed, 22.47 expected, observed/expected ratio (o/e) 0.58, 90% interval 0.38 to 0.92. The upper end of that interval is the gene's LOEUF score, 0.92, which puts it in group 3 of 6, group 1 being the genes least tolerant of losing a copy. Missense variants: 364 observed, 520.75 expected, observed/expected ratio (o/e) 0.7, 90% interval 0.64 to 0.76. Synonymous variants: 219 observed, 236.21 expected, observed/expected ratio (o/e) 0.93, 90% interval 0.83 to 1.04.
Homologues: Orthologues: chimpanzee GPR4 (100% identical), macaque GPR4 (99% identical), dog GPR4 (97% identical), pig GPR4 (95% identical), rabbit GPR4 (93% identical), rat Gpr4 (93% identical), mouse Gpr4 (92% identical), zebrafish gpr4 (67% identical), tropical clawed frog gpr4 (47% identical), Caenorhabditis elegans gnrr-4 (19% identical). Paralogues in human: GPR65 (36% identical), GPR17 (26% identical), F2RL3 (24% identical), LPAR6 (24% identical), F2RL1 (23% identical), LPAR4 (23% identical), CYSLTR1 (22% identical), GPR35 (22% identical), CYSLTR2 (21% identical), F2RL2 (21% identical), GPR18 (21% identical), P2RY10 (21% identical), and 4 more.
Diseases named in the same sentence as GPR4 in open-access papers:
GPR4 is named in the same sentence as 72 diseases in open-access papers, as found by Europe PMC text mining. Sharing a sentence is not in itself a finding about the gene and the disease. The quoted sentences say what the papers report.
ovarian carcinoma (28 papers, 2013 to 2025). A malignant neoplasm originating from the surface ovarian epithelium. "This includes G-protein receptor 4 (GPR4), T cell death-associated gene 8 (TDAC8, or GPR65), and ovarian cancer G-protein coupled receptor 1 (OGR1, or GPR68)." (PMID 41091845, 2025). "Proton-sensing GPCRs—notably GPR4, GPR65 (also known as T-cell death-associated gene 8, TDAG8), and GPR68 (also known as ovarian cancer G-protein-coupled receptor 1, OGR1)—are transmembrane receptors that detect extracellular acidification." (PMID 41375084, 2025). "G protein-coupled receptors (GPRs), including pro-inflammatory GPR4 and ovarian cancer GPR1 (OGR1/GPR68), are involved in the pH sensing of the extracellular space and have been implicated in inflammatory bowel disease (IBD)." (PMID 40004018, 2025). "For example, in ovarian cancer cells, downregulation of GPR4 inhibits cancer cell invasion, thus confirming that GPR4 plays a promoting role in ovarian cancer cell invasion." (PMID 38505262, 2024). "pHRs are class A GPCRs that consist of three members, G protein coupled receptor 4 (GPR4), T cell death-associated gene 8 (TDAG8, aka GPR65) and ovarian cancer G-protein coupled receptor 1 (OGR1, aka GPR68)." (PMID 38340167, 2024). "There are four members within this family of receptors, the Ovarian Cancer G-Protein Coupled Receptor Protein1 (OGR1, GPR68), G-protein Coupled Receptor 4 (GPR4), G2 accumulation (G2A, GPR132), and T Cell Death-Associated Gene 8 (TDAG8, GPR65)." (PMID 36010617, 2022). "Here, we analyzed the roles of proton-sensing G protein-coupled receptors, including T-cell death-associated gene 8 (TDAG8), ovarian cancer G protein-coupled receptor 1 (OGR1), and G protein-coupled receptor 4 (GPR4) in a mouse ischemia reperfusion model." (PMID 33057165, 2020). "GPR4 is also involved in the progression of head and neck cancer, epithelial ovarian cancer (EOC) and colorectal cancer." (PMID 31683697, 2019). "GPR4 is overexpressed in various types of malignancies including breast cancers, ovarian cancers, colon cancers, liver cancers and kidney cancers." (PMID 27078157, 2016). "In addition, GPR4 is also known to play an important role in ovarian cancer growth and angiogenesis." (PMID 38505262, 2024). "Extracellular acidosis is signaled by the Ovarian Cancer G-Protein Coupled Receptor (OGR) family of cell surface receptors, including OGR-1, T-cell death associated gene-8 (TDAG-8) and G-protein coupled receptor-4 (GPR-4)." (PMID 37418488, 2023). "This subfamily of proteins is composed of four members: G protein-coupled receptor 4 (GPR4 or Gpr4), T-cell death–associated gene 8 (TDAG8 or Gpr65), ovarian cancer G protein–coupled receptor 1 (OGR1 or Gpr68), and G protein–coupled receptor 132 (G2A or Gpr132)." (PMID 35247105, 2022). "The family of GPCR includes the ovarian cancer G protein-coupled receptor 1 (OGR1, also known as GPR68), the G protein-coupled receptor 4 (GPR4), the T cell death-associated G protein 8 (TDAG8, also known as GPR65), and the G2 accumulation protein (G2A, also known as GPR132)." (PMID 30825056, 2019). "Ovarian cancer G protein-coupled receptor 1 (OGR1), T cell death-associated gene 8 (TDAG8), G protein coupled receptor 4 (GPR4) and G2 accumulation (G2A) are all belong to proton-sensing GPCRs family, they share 40–50% homology with different action modes and signaling pathways." (PMID 28332558, 2017). "In response to acidic extracellular pH, GPR65 induces an anti-inflammatory response, whereas the two other proton-sensing receptors, GPR4 and GPR68 (ovarian cancer G protein-coupled receptor 1, OGR1), mediate pro-inflammatory responses." (PMID 38514581, 2024). "Downregulation of GPR4 leads to a downregulation of TCF7, inhibiting cell growth and cell invasion, and promoting apoptosis of ovarian cancer cells." (PMID 36902589, 2023).
ovarian carcinoma (continued). "Human ovarian cancer G-protein-coupled receptor 1 (hOGR1) and GPR4 (hGPR4) can bind to extracellular protons, leading to activation of intracellular signalling pathways through G proteins." (PMID 36611913, 2022). "Consistent with the results in prostate and ovarian cancer cells, GPR4 did not significantly affect MCF7 cell migration even though it shares approximately 54% homology with OGR1." (PMID 23663350, 2013).
colitis (11 papers, 2017 to 2025). Inflammation of the colon. "Previous data show that a loss of GPR4 or OGR1 independently is associated with reduced intestinal inflammation in mouse models of experimental colitis." (PMID 40004018, 2025). "The deletion of GPR4 in mouse models of experimental colitis has been associated with decreased mucosal leukocyte infiltration and reduced intestinal inflammation." (PMID 40004018, 2025). "In mice, Gpr4 deficiency protects against inflammation and fibrosis in the spontaneous interleukin 10 knockout (Il10‐/‐) colitis model." (PMID 40397803, 2025). "Our results demonstrate that the knockout of GPR4 alleviates intestinal inflammation and impedes the development of colitis-associated colorectal cancer in mouse models." (PMID 37894341, 2023). "To further study the role of GPR4 in the development of colitis-associated colorectal cancer (CAC), we utilized the well-established AOM/DSS murine model." (PMID 37894341, 2023). "In this study, we demonstrate that GPR4-driven intestinal inflammation can increase the development of colorectal tumorigenesis in a colitis-associated colorectal cancer mouse model." (PMID 37894341, 2023). "To confirm the interaction of GPR4 and OGR1 in the development of intestinal inflammation we applied the spontaneous colitis model which is driven by IL10 deficiency." (PMID 40004018, 2025). "Il10−/− (n = 17), Il10−/− × Gpr4−/− (n = 13), Il10−/− × Ogr1−/− (n = 10), and Il10−/− × Gpr4−/− × Ogr1−/− (n = 10) developed colitis after approximately 190 days." (PMID 40004018, 2025). "While the anti-inflammatory effects of GPR4 antagonists have been shown in other models of inflammatory diseases, such as arthritis and colitis, the anti-viral effects were first uncovered in this study." (PMID 40703349, 2025). "To study the effects of combined loss of Gpr4 Ogr1 in IBD we used the well-established acute dextran sodium sulfate (DSS) and spontaneous Il10−/− murine colitis models." (PMID 40004018, 2025). "Deletion of GPR4 in mouse models of experimental colitis decreased the expression of the endothelial adhesion molecules, vascular cell adhesion molecule-1 (VCAM1), and E-selectin in the intestinal microvasculature." (PMID 38514581, 2024). "In this context, it is important to note that pharmacological tools already exist to inhibit GPR4, and these molecules have been successfully tested in several animal models, including models of colitis (, and chapter below)." (PMID 38514581, 2024). "We and others previously elucidated the role of GPR4 in potentiating intestinal inflammation by using both GPR4 antagonists and global GPR4 knockout mice in colitis mouse models." (PMID 37894341, 2023). "Herein, we evaluated the proinflammatory role of GPR4 in the development of colitis-associated colorectal cancer (CAC) using the dextran sulfate sodium (DSS) and azoxymethane (AOM) mouse models in wild-type and GPR4 knockout mice." (PMID 37894341, 2023). "Murine models also demonstrated a critical role for GPR4 in promoting angiogenesis following tumor injection or colitis induction." (PMID 36611126, 2023). "In this study, we demonstrated that GPR4 increased intestinal inflammation in DSS chronic colitis and AOM/DSS colitis-associated colorectal cancer mouse models." (PMID 37894341, 2023). "We used WT and GPR4 KO mice to characterize the role of GPR4 in the chronic DSS-induced colitis mouse model." (PMID 37894341, 2023). "We previously showed that GPR4 antagonists in the DSS-induced colitis mouse model reduced TNF-α mRNA levels in intestinal tissues when compared with a vehicle control." (PMID 37894341, 2023). "In the DSS-induced acute colitis model, GPR4 antagonist 13 (NE-52-QQ57) ameliorates intestinal inflammation and decreases the expression of TNF-α in the inflamed mouse colon tissues." (PMID 33553219, 2020). "Using GPR4 knockout (KO) mice, studies demonstrated that GPR4 deletion reduces inflammation in mouse colitis models." (PMID 33553219, 2020).
colitis (continued). "Our recent publication highlights GPR4 as being pro-inflammatory within inflamed intestinal tissues, as the deletion of GPR4 reduces intestinal inflammation in an acute experimental colitis model." (PMID 28134810, 2017). "Earlier studies suggest that GPR4 supports inflammation; we therefore hypothesized that inflammation and spontaneous tumor development would be reduced in the AOM/DSS model of colitis‐induced cancer in Gpr4‐deficient animals." (PMID 40397803, 2025). "Furthermore, GPR4 gene expression was upregulated three-fold in the WT-DSS mouse colon samples compared with the WT control, consistent with upregulation of GPR4 expression observed in other mouse colitis models and IBD patient samples." (PMID 37894341, 2023). "GPR4 is a proton-sensing G protein-coupled receptor highly expressed in vascular endothelial cells and has been shown to potentiate intestinal inflammation in murine colitis models." (PMID 37894341, 2023). "In the present study, we investigated the role of the pro-inflammatory proton-sensing receptors GPR4 and OGR1 using well-established murine models of acute and spontaneous colitis." (PMID 40004018, 2025). "Briefly, 12–15-week-old WT (n = 22), Gpr4−/− (n = 9), Ogr1−/− (n = 14), and Gpr4−/− × Ogr1−/− × (n = 4) littermate mice were exposed to DSS for 8 days, resulting in pronounced colitis." (PMID 40004018, 2025). "Moreover, deletion of GPR68 or GPR4 ameliorates gut mucosal inflammation in mouse model of colitis, indicating these proton‐activated GPCRs may act as a proinflammatory role in the development of colitis." (PMID 35343079, 2022). "Another study also demonstrated that GPR4 deletion alleviates intestinal inflammation in the DSS-induced colitis and the IL10-/- spontaneous colitis mouse models." (PMID 33553219, 2020). "GPR4 deletion reduces the expression of endothelial adhesion molecules E-selectin and VCAM-1 in the colon of the DSS-induced colitis mice." (PMID 33553219, 2020). "Furthermore, GPR4 mRNA expression levels are significantly increased in the inflamed intestinal tissues of both human IBD patients and in colitis mouse models when compared with normal tissues." (PMID 37894341, 2023). "The absence of GPR4 ameliorates colitis with lower histology scores, reduced CD4+ T helper cell infiltration, and decreased IFN-γ, iNOS, CXCL1, and CXCL2 expression." (PMID 35165253, 2022).
melanoma (9 papers, 2013 to 2024). A malignant, usually aggressive tumor composed of atypical, neoplastic melanocytes. "It was also shown in melanoma cells that signaling of the G-protein coupled H+ receptor GPR4 linked the activity of FAK to the ambient pH." (PMID 37566113, 2023). "GPR4 has also been implicated in the alteration of cell metabolism in B16F10 melanoma cells." (PMID 25988385, 2015). "Alternatively, overexpression of GPR4 in mouse B16F10 melanoma cells reduced cell migration and metastasis, although primary tumor growth was not significantly affected." (PMID 39336742, 2024). "GPR4 has been investigated in various types of cancer such as melanoma, epithelial ovarian carcinoma, head-and-neck cancer, and colon cancer." (PMID 39336742, 2024). "In melanoma and prostate cancer cells, ectopic expression of GPR4 activated by acidic pH decreases migration and melanoma lung metastases, but it does not significantly decrease growth of the primary tumour." (PMID 36046070, 2020). "In contrast, GPR4 overexpression in B16F10 melanoma cells inhibited their acidic pH-induced migration, invasion and metastasis formation." (PMID 32948783, 2020). "In a study of B16F10 melanoma cells that over-express GPR4, the maximal oxygen consumption rate (OCR) of mitochondria was increased." (PMID 25988385, 2015). "The migration of GPR4 overexpressing melanoma cells is enhanced in an acidic microenvironment." (PMID 38233872, 2024). "However, the opposite result was found in another study, when GPR4 was overexpressed in mouse B16F10 melanoma cells, acidosis-activated GPR4 inhibited cancer cell migration and reduced melanoma cell lung metastasis." (PMID 38505262, 2024). "A recent study also showed that GPR4 is involved in the migration of melanoma cells and is enhanced in the range of pH 6.5 to 7.5, suggesting that an acidic microenvironment may promote melanoma invasion and metastasis through GPR4." (PMID 38505262, 2024). "GPR4 is overexpressed in squamous cell carcinoma of the head and neck, colorectal cancer, breast, ovarian, colon, liver and kidney tumors, Merkel cell carcinoma and melanoma." (PMID 38233872, 2024). "Similarly, in melanoma cells, the effect of GPR4 on tumor cell migration was opposite in the two studies." (PMID 38505262, 2024). "GPR4 over-expression reduced lung metastasis of B16F10 melanoma cells in C57BL/6 mice." (PMID 25988385, 2015). "Treatment with the GPR4 antagonist NE-52-QQ57 reduced the lymphangiogenesis and lymph-node metastasis of melanoma cells in a mouse cancer metastasis model." (PMID 39336742, 2024). "To better understand the functions of pH-GPCRs in skin cancer in vivo, we examined the expression-profiles of GPR4, TDAG8, OGR1 and G2A in four common skin tumors, i.e. squamous cell carcinoma (SCC), malignant melanoma (MM), compound nevus cell nevi (NCN), basal cell carcinoma (BCC)." (PMID 32948783, 2020). "Likewise, GPR4 can reduce migration and metastasis of mouse B16F10 melanoma- and TRAMP-C1 prostate cells in vitro but does not inhibit B16F10 melanoma growth." (PMID 34440817, 2021).
Acidosis (8 papers, 2011 to 2025). Abnormal acid accumulation or depletion of base. "Acidosis–GPR4 signaling induces endothelial adhesion molecules and broad inflammatory gene programs via cAMP/EPAC → NF-κB; small-molecule GPR4 antagonists suppress these responses in vitro, nominating GPR4 as a druggable node of acid-driven inflammation." (PMID 41148822, 2025). "Acidosis activates a family of proton sensing G-protein coupled receptors, including G-protein coupled receptor 4 (GPR4), G-protein coupled receptor 65 (GPR65), G-protein coupled receptor 68 (GPR68), and G-protein coupled receptor 132 (GPR132)." (PMID 25988385, 2015). "Acidosis/GPR4-mediated inflammatory gene expression appears to be general in several types of vascular endothelial cells." (PMID 23613998, 2013). "Acidosis/GPR4 signaling also up-regulates the expression of several adhesion molecules in endothelial cells." (PMID 22110680, 2011). "Acidosis in combination with GPR4 overexpression further augments HUVEC adhesion with U937 monocytes." (PMID 22110680, 2011). "Acidosis/GPR4 stimulated the expression of ICAM-1, however, to a lesser extent as there was both a minor increase in HUVEC/Vector cells and an increase of 10-fold in HUVEC/GPR4 cells." (PMID 22110680, 2011).